ADCY10 (adenylate cyclase 10)
Description:
Catalyzes the formation of the signaling molecule cAMP. May function as sensor that mediates responses to changes in cellular bicarbonate and CO(2) levels. Has a critical role in mammalian spermatogenesis by producing the cAMP which regulates cAMP-responsive nuclear factors indispensable for sperm maturation in the epididymis. Induces capacitation, the maturational process that sperm undergo prior to fertilization (By similarity). Involved in ciliary beat regulation.
Synonyms: hsAC; sAC; Sacy; SACI; HCA2; RP1-313L4.2; HEL-S-7a
Tractability: Small molecule: a structure with a bound ligand is known; a high-quality ligand is known. Antibody: UniProt places it where antibodies can reach, with high confidence; its Gene Ontology location is reachable by antibodies, with medium confidence. PROTAC: a small molecule that binds it is known.
Target class: Enzyme; Lyase
Chemical probes: TDI-10229
Gene: Protein-coding gene on chromosome 1 (167,809,386 to 167,914,215, reverse strand). Ensembl gene ENSG00000143199.
Subcellular location: Cell membrane; Cytoplasm, cytoskeleton; Cytoplasm, perinuclear region; Nucleus; Cell projection, cilium; Cytoplasm; Mitochondrion
Pathways (Reactome):
Signal Transduction: Hedgehog 'off' state
Gene Ontology:
Molecular function: adenylate cyclase activity; bicarbonate binding; molecular sensor activity; ATPase binding; magnesium ion binding; manganese ion binding
Biological process: cAMP biosynthetic process; cellular response to carbon dioxide; epithelial cilium movement involved in extracellular fluid movement; regulation of intracellular pH; adenylate cyclase-activating G protein-coupled receptor signaling pathway; adenylate cyclase-inhibiting G protein-coupled receptor signaling pathway; cyclic nucleotide biosynthetic process; glucose catabolic process; intracellular signal transduction; mitochondrial ATP transmembrane transport; negative regulation of cardiac muscle cell contraction; negative regulation of mitochondrial membrane potential; negative regulation of reactive oxygen species biosynthetic process; neuron projection extension; neuron projection maintenance; neuron projection retraction; positive regulation of apoptotic process; positive regulation of ATP biosynthetic process; positive regulation of axon extension; positive regulation of cardiac muscle cell apoptotic process; positive regulation of cardiac muscle hypertrophy; positive regulation of establishment of protein localization to mitochondrion; positive regulation of glycogen catabolic process; positive regulation of intrinsic apoptotic signaling pathway; positive regulation of mitochondrial depolarization; and 8 more
Cellular component: cytoplasm; microtubule cytoskeleton; mitochondrion; motile cilium; nucleus; perinuclear region of cytoplasm; plasma membrane; cytosol; apical part of cell; astrocyte end-foot; axon; basal part of cell; central region of growth cone; cilium; cytoskeleton; dendrite; extracellular region; growth cone; neuronal cell body
Genetic constraint (gnomAD): Loss-of-function variants: 143 observed, 178.13 expected, observed/expected ratio (o/e) 0.8, 90% interval 0.7 to 0.92. The upper end of that interval is the gene's LOEUF score, 0.92, which puts it in group 3 of 6, group 1 being the genes least tolerant of losing a copy. Missense variants: 1,715 observed, 1,998.3 expected, observed/expected ratio (o/e) 0.86, 90% interval 0.82 to 0.89. Synonymous variants: 633 observed, 696.06 expected, observed/expected ratio (o/e) 0.91, 90% interval 0.85 to 0.97.
Homologues: Orthologues: chimpanzee ADCY10 (99% identical), macaque ADCY10 (93% identical), rabbit ADCY10 (81% identical), dog ADCY10 (80% identical), pig ADCY10 (80% identical), rat Adcy10 (77% identical), mouse Adcy10 (77% identical), guinea pig ADCY10 (67% identical).
Diseases named in the same sentence as ADCY10 in open-access papers:
ADCY10 is named in the same sentence as 38 diseases in open-access papers, as found by Europe PMC text mining. Sharing a sentence is not in itself a finding about the gene and the disease. The quoted sentences say what the papers report.
male infertility (5 papers, 2015 to 2025). The inability of the male to effect fertilization of an ovum after a specified period of unprotected intercourse. "In addition to mice, clinical studies link pathogenic variants in SLC9C1 or ADCY10 to asthenozoospermia and male infertility in humans." (PMID 41091759, 2025).
lung carcinoma (4 papers, 2020 to 2025). "Interestingly, a previous study has found that adenylyl cyclase, particularly ADCY10, is linked to ferroptosis in lung cancer." (PMID 40725190, 2025). "These proteins include LTN1 (ovarian cancer), GBE1, CACNA1E and ADCY10 (lung cancers), as well as PLEKHS1 and ADNP (bladder cancer)." (PMID 38951817, 2024). "Mechanically, glutamate accumulation stimulates Ca2+-dependent activation of ADCY10, which mediates cAMP production and subsequent activation of protein kinase A (PKA) pathway, ultimately leading to the inhibition of YAP in lung cancer cells." (PMID 34742351, 2021). "Adenylate cyclase 10 (ADCY10) suppresses YAP and therefore sensitizes lung cancer cells to induction of ferroptosis; this is done through inhibiting ferritin by transcription or activation of ferritinophagy-dependent degradation and consequently elevating iron." (PMID 34742351, 2021).
breast carcinoma (2 papers, 2011 to 2025). "ADCY10 mutations have been identified in multiple cancers, including Merkel cell carcinoma and breast cancer." (PMID 40725190, 2025).
diabetes (2 papers, 2017 to 2022). "One may speculate that targeted orchestration of ADCY10 under conditions of impaired cell metabolism and endothelial regenerative dysfunction, as found, for example, in diabetes mellitus may become a possible therapeutic option." (PMID 36372953, 2022).
asthenozoospermia (1 paper, 2020). "ADCY10 (Adenylate Cyclase 10) mapping on the chromosome 1q24.2, encodes for soluble adenylyl cyclase, which is the predominant adenylate cyclase in sperm crucial to sperm motility regulation, and it is associated with severe recessive asthenozoospermia." (PMID 33574797, 2020).
lung adenocarcinoma (1 paper, 2025). A carcinoma that arises from the lung and is characterized by the presence of malignant glandular epithelial cells. "Adenosine cyclase ADCY10 is highly expressed in lung adenocarcinoma, and it promotes the development of lung adenocarcinoma and also induces ferroptosis sensitivity of tumor cells." (PMID 40050614, 2025).
tumor (14 papers, 2009 to 2025). "Limiting dilution cell transplantation assays demonstrated that ADCY10 deficiency in H1975 cells also decreased the frequency of tumor incidence in mice." (PMID 33897873, 2021). "As expected, the upregulation of ADCY10 was associated with tumor stage in human LUADs." (PMID 33897873, 2021). "This might be because many targets of ferroptosis (including SLC7A11, YAP, and ADCY10) are positively correlated with tumor progression, and they guarantee the outbreak of cell ferroptosis after receiving an external ferroptosis-promoting signal." (PMID 34765600, 2021). "Knocking down ADCY10 by two independent shRNAs significantly impaired anchorage-independent growth of H1975 cells in soft agar, spheroid formation in 3D culture and tumor growth in CDX mouse models." (PMID 33897873, 2021). "Other genes such as KL, MNX1, HMCN1 and ADCY10 suggest that anoikis resistance is not restricted to survival pathways but also extends to metabolic and proliferative mechanisms that drive both tumour aggressiveness and treatment resistance." (PMID 40830065, 2025). "We found that IKE was ineffective in further reducing tumor growth, increasing MDA concentration or prolonging OS time once upon ADCY10 expression was impaired, suggesting that the expression of ADCY10 is essential for the efficacy of ferroptosis-based therapy in vivo." (PMID 33897873, 2021).
cancer (10 papers, 2015 to 2025). A tumor composed of atypical neoplastic, often pleomorphic cells that invade other tissues.
ADCY10 also shares sentences with these, for which no sentence is quoted: Infertility (6 papers); infection (3); Hypercalciuria (2); osteoporosis (2); ovarian carcinoma (2); prostate carcinoma (2); acute pancreatitis (1); Azoospermia (1); bladder cancer (1); cardiac hypertrophy (1); colon carcinoma (1); colorectal cancer (1); glaucoma (1); glioblastoma (1); hepatoma (1); hydatidosis (1); idiopathic hypercalciuria (1); insulinoma (1); ischemia (1); Merkel cell carcinoma (1); nephrolithiasis (1); neuroblastoma (1); non-small cell lung carcinoma (1); ovarian disorder (1); pancreatitis (1); papilloma (1); prostate adenocarcinoma (1); rectum (1); retinal diseases (1); squamous cell carcinoma (1).